RNU6-899P (RNA, U6 small nuclear 899, pseudogene)
Gene: Small nuclear RNA gene on chromosome 11 (58,026,706 to 58,026,812, reverse strand). Ensembl gene ENSG00000200817.
Homologues: Orthologues: chimpanzee U6 (99% identical), dog U6 (88% identical), macaque U6 (88% identical), rat U6 (87% identical), rabbit U6 (79% identical). Paralogues in human: RNU6-15P (89% identical), RNU6-211P (89% identical), RNU6-1024P (88% identical), RNU6-1060P (88% identical), RNU6-1152P (88% identical), RNU6-17P (88% identical), RNU6-18P (88% identical), RNU6-19P (88% identical), RNU6-21P (88% identical), RNU6-480P (88% identical), RNU6-1 (87% identical), RNU6-116P (87% identical), and 1287 more.